OR4B1 (olfactory receptor family 4 subfamily B member 1)
Description:
Odorant receptor.
Synonyms: OST208; OR11-106
Tractability: Antibody: UniProt places it where antibodies can reach, with medium confidence; UniProt predicts a signal peptide or a membrane-spanning region; its Gene Ontology location is reachable by antibodies, with medium confidence.
Gene: Protein-coding gene on chromosome 11 (48,216,810 to 48,217,739, forward strand). Ensembl gene ENSG00000175619.
Subcellular location: Cell membrane
Pathways (Reactome):
Sensory Perception: Expression and translocation of olfactory receptors
Gene Ontology:
Molecular function: olfactory receptor activity; G protein-coupled receptor activity
Biological process: detection of chemical stimulus involved in sensory perception of smell; G protein-coupled receptor signaling pathway
Cellular component: plasma membrane; membrane
Genetic constraint (gnomAD): Loss-of-function variants: 1 observed, 0.16 expected, observed/expected ratio (o/e) 6.43. That is too few expected variants to judge how well the gene tolerates losing a copy. Missense variants: 520 observed, 389.88 expected, observed/expected ratio (o/e) 1.33, 90% interval 1.24 to 1.43. Synonymous variants: 196 observed, 149.18 expected, observed/expected ratio (o/e) 1.31, 90% interval 1.17 to 1.48.
Homologues: Orthologues: chimpanzee OR4B1 (98% identical), pig OR4B1 (86% identical), dog OR4B1 (85% identical), rabbit OR4B1 (85% identical), rat Or4b1c (82% identical), rat Or4b1 (82% identical), mouse Or4b1 (81% identical), rat Or4b1d (80% identical), mouse Or4b1c (80% identical), mouse Or4b1d (80% identical), mouse Or4b1b (79% identical), mouse Or4b13 (78% identical), and 2 more. Paralogues in human: OR4S2 (61% identical), OR4X2 (59% identical), OR4X1 (57% identical), OR4C12 (57% identical), OR4C6 (57% identical), OR4C46 (56% identical), OR4C13 (56% identical), OR4C15 (56% identical), OR4C5 (56% identical), OR4A5 (55% identical), OR4C11 (55% identical), OR4C3 (55% identical), and 116 more.
Diseases named in the same sentence as OR4B1 in open-access papers:
OR4B1 is named in the same sentence as 1 disease in open-access papers, as found by Europe PMC text mining. Sharing a sentence is not in itself a finding about the gene and the disease. The quoted sentences say what the papers report.
Dystonia (1 paper, 2021). An abnormally increased muscular tone that causes fixed abnormal postures. "Some genome-wide association studies (GWASs) and replication studies have revealed correlations between single nucleotide polymorphisms (SNPs) of the ARSG, BDNF, NALCN, OR4X2, KIAA1715, and OR4B1 genes and dystonia." (PMID 35273550, 2021).